IFITM1 (interferon induced transmembrane protein 1)
Diseases named in the same sentence as IFITM1 in open-access papers (continued):
Sharing a sentence is not in itself a finding about the gene and the disease.
Obesity (2 papers, 2015 to 2022). Accumulation of substantial excess body fat. "This approach revealed that the expression of IFITM1 was higher in patients who reported tobacco use, whereas a reduction in this gene was observed in those with obesity and exposure to biomass smoke, although the differences were not significant." (PMID 35708622, 2022).
oral squamous cell carcinoma (2 papers, 2023 to 2024). "We recently reported that one lncRNA, DLEU1, exerts oncogenic effects in oral squamous cell carcinoma through activation of IFITM1, one of the IRDS genes." (PMID 37443145, 2023).
pituitary adenoma (2 papers, 2023 to 2025). "Moreover, circVPS13C interacts with RRBP1 to increase pituitary adenoma growth by reducing the stability of IFITM1 mRNA." (PMID 40612865, 2025).
primary Sjögren syndrome (2 papers, 2014 to 2022). "Additionally, genes related to type I-IFN activity including, ICSBP1, MX1, IFITM1, IFITM2, IRF9, were found to be overexpressed in patients with Sjogren’s syndrome." (PMID 36059459, 2022).
respiratory infection (2 papers, 2020 to 2022). "However, bulk IFITM1 and IFITM3 mRNA expression dynamics and their correlation with clinical outcomes have not been extensively addressed in patients with respiratory infections." (PMID 35708622, 2022).
Sepsis (2 papers, 2022 to 2025). Sepsis is defined as life-threatening organ dysfunction caused by a dysregulated host response to infection. "Our platelet transcriptomic and proteomic data indicate other IFITMs, including IFITM1 and IFITM2, are also increased in sepsis and IFN-induced inflammation." (PMID 36194487, 2022).
Stroke (2 papers, 2022 to 2025). Sudden impairment of blood flow to a part of the brain due to occlusion or rupture of an artery to the brain. "We next examined the expression profile of IFITM family members (Ifitm1, Ifitm2, and Ifitm3) in the post-stroke brain of aged mice." (PMID 36012150, 2022). "In addition, Rep-Mo/MΦ demonstrated the enrichment of “response to interferon-gamma” genes (Ifitm1 and Ifitm6), which has been shown to promote microglial migration and exacerbate brain injury of stroke." (PMID 40777042, 2025).
triple-negative breast carcinoma (2 papers, 2023 to 2025). An invasive breast carcinoma which is negative for expression of estrogen receptor (ER), progesterone receptor (PR), and human epidermal growth factor receptor 2 (HER2). "Similarly, IFITM1 expression is regulated by interferon-alpha/NF-κB signaling, and its suppression has been shown to reduce tumor growth and invasion in triple-negative breast cancer." (PMID 40646573, 2025).
acute coronary syndrome (1 paper, 2025). Signs and symptoms related to acute ischemia of the myocardium secondary to coronary artery disease. "This differential expression profile suggests a potential pathophysiological role for IFITM1 in post-infarction ventricular remodeling and heart failure development, whereas IFITM2/3 appear more broadly associated with acute coronary syndrome pathogenesis." (PMID 41368318, 2025).
acute kidney injury (1 paper, 2025). Sudden and sustained deterioration of the kidney function characterized by decreased glomerular filtration rate, increased serum creatinine or oliguria. "Further significantly upregulated transcripts related to inflammatory processes included ADAM19, PD-L1 (CD274), non-canonical NF-kB genes NFKB2 and RELB, furthermore IFITM1, JAML -linked with acute kidney injury - IRX3-linked with metabolic inflammation - and PRDM1-observed in gouty arthritis." (PMID 40281125, 2025).
acute myocardial infarction (1 paper, 2025). Necrosis of the myocardium, as a result of interruption of the blood supply to the area. "Significantly higher IFITM1/2/3 levels in AMI patients compared with CAD and control groups suggest their involvement in acute myocardial infarction responses." (PMID 41368318, 2025).
adenoma (1 paper, 2021). A neoplasm arising from the epithelium. "We also show that Ifitm1 expression is increased after Apc mutation, similarly to human adenomas when compared to normal colonic epithelium." (PMID 34609520, 2021). "Here we prove that human organoids derived from adenomas or CRC patients express IFITM1 at a higher level compared to the normal colon." (PMID 34609520, 2021).
alopecia (1 paper, 2022). Hair loss usually from the scalp. "The present study showed that IFITM1 has the ability to predict disease activity and identify patients with alopecia." (PMID 35757684, 2022).
avian influenza (1 paper, 2015). Infection of domestic and wild fowl and other birds with influenza A virus. "In ducks, IFITM1, 2 and 3 are strongly up regulated in response to highly pathogenic avian influenza, where little response is seen in chickens." (PMID 26238195, 2015). "The results of this study confirm the involvement of avian IFITM1, 2 and 3 in the host response to avian influenza LPAI and HPAI viruses." (PMID 26238195, 2015).
bipolar disorder (1 paper, 2021). A disorder of the brain that causes unusual shifts in mood, energy, activity levels and the ability to carry out day-to-day tasks. "In addition, mRNA levels were higher in 71% (IFITM1) and 71% (IFITM2/3) of bipolar disorder subjects relative to their matched comparison subjects." (PMID 33436571, 2021). "Furthermore, IFITM1 mRNA levels were correlated with mRNA levels for IL-1R, TNFR, NF-κB2, and RelA across all subjects (all r ≥ 0.41, all p ≤ 0.004) and in bipolar disorder subjects alone (all r ≥ 0.60, all p ≤ 0.0001)." (PMID 33436571, 2021).
coronary stenosis (1 paper, 2025). Narrowing of the coronary artery lumen diameter. "This retrospective clinical cohort study was performed to explore the association of IFITM1/2/3 with coronary stenosis severity and to evaluate the diagnostic accuracy of circulating IFITMs for identifying CAD and AMI patients." (PMID 41368318, 2025). "IFITM1/2/3 may serve as novel serum biomarkers for diagnosing CAD and AMI, as well as stratifying coronary stenosis severity, with high discriminatory capacity." (PMID 41368318, 2025).
fibrosis (1 paper, 2025). the formation of excess fibrous connective tissue in an organ or tissue in a reparative or reactive process. "Thirty days post-laminectomy, IFITM1-KO mice exhibited significantly more extensive epidural fibrosis." (PMID 40969741, 2025).
Flavivirus Infections (1 paper, 2021). Infections with viruses of the genus FLAVIVIRUS, family FLAVIVIRIDAE. "According to a previous study involving flavivirus infection, the mRNA levels of six key ISGs, i.e., IFITM1, IFITM3, OASL2, PKR, VIPERIN, and ISG15, were analyzed by real-time PCR in the spleen and liver." (PMID 35310394, 2021).
fungal infections (1 paper, 2020). "Interestingly, we found that AmphoB, an anti-mycotic drug commonly used for systemic fungal infections, could dramatically enhanced the cell entry of SARS-CoVs and SL-CoVs, and completely blocked IFITM3-mediated restriction, but did not affect IFITM1-mediated restriction." (PMID 32602823, 2020).
heart failure (1 paper, 2025). Inability of the heart to pump blood at an adequate rate to meet tissue metabolic requirements. "Another notable finding is that IFITM1 is selectively upregulated in post-AMI heart failure and negatively correlated with Ejection Fraction (EF) or Fractional Shortening (FS), which warrants attention." (PMID 41368318, 2025). "The specific upregulation of IFITM1 in post-AMI heart failure suggests a potential distinct role in maladaptive remodeling." (PMID 41368318, 2025). "Notably, elevated IFITM1 levels in post-AMI heart failure patients suggested its potential role in post-AMI cardiac decompensation mechanisms." (PMID 41368318, 2025). "AMI patients exhibited further elevation of IFITM1/2/3 compared to patients with stable CAD (p < 0.0001), with IFITM1 specifically upregulated in AMI with heart failure (3.07 vs. 4.64 ng/mL, p = 0.003)." (PMID 41368318, 2025).
Hurler disease (1 paper, 2012). "In MPS I mice (a model of Hurler disease caused by alpha-L-iduronidase deficiency) both HS and DS accumulate and the mice have similar changes in microglial activation genes as MPS IIIb; however, genes associated with inflammation are not up-regulated (e.g. Ifitm1, Ifnar2 )." (PMID 22403656, 2012).
influenza A(H1N1) virus infection (1 paper, 2022). "In this study, we evaluated whether the bulk mRNA expression of IFITM1 and IFITM3 showed a particular pattern and dynamics during active severe pandemic influenza A(H1N1) virus infection in humans." (PMID 35708622, 2022).
kidney injury (1 paper, 2023). Trauma to the kidney. "Expression of ISGs (Mx1, Isg15, Isg20, Ifitm1, Bst2, and Oas1), and immune cell markers Lyz2 and Cd68 were markedly lower in 3TC mice with FA-induced kidney injury compared to controls." (PMID 36732547, 2023).
Listeria infection (1 paper, 2012). "In addition, we find that functional Ifitm1 is not necessary for normal somite formation and development as well as for a normal immune response even under conditions of Listeria infection." (PMID 23115618, 2012).
lung diseases (1 paper, 2024). "A recent study demonstrated that nine genes (CD274, CEACAM1, CR1, FCGR1A/B, IFITM1, IRAK3, LILRA6, MAPK14, and PDCD1LG2) showed 100% sensitivity and specificity that distinguished patients with active TB from those with other lung diseases (OPD)." (PMID 38674369, 2024).
metastatic colorectal cancer (1 paper, 2016). "Here, we show that IFITM1 is highly expressed in metastatic colorectal cancer cell lines as well as colorectal patient-derived tumor samples, and its expression is associated with a poor prognosis of the disease." (PMID 27852071, 2016).
metastatic melanoma (1 paper, 2021). A melanoma that has spread from its primary site to another anatomic site. "However, the expression levels of IFITM1 (P = 0.643) and GBP2 (P = 0.320) were not significantly different between primary and metastatic melanoma tissues." (PMID 33688507, 2021).
monoclonal gammopathy of undetermined significance (1 paper, 2026). "We observed that expression of both INSR and IFITM1 was significantly elevated in symptomatic MM patients compared with those with monoclonal gammopathy of undetermined significance (MGUS) and smouldering MM (SMM)." (PMID 42286874, 2026).
osteogenesis imperfecta type 5 (1 paper, 2022). Osteogenesis imperfecta type V is a moderate type of osteogenesis imperfecta (OI), a genetic disorder characterized by increased bone fragility, low bone mass and susceptibility to bone fractures with variable severity. "The A subfamily is composed of the IFN-inducible and antiviral IFITM1, 2 and 3, as well as of IFITM5 and IFITM10, which are not IFN regulated and that in the case of IFITM5 are associated to Osteogenesis imperfecta type V, a bone-related genetic disease." (PMID 35396335, 2022).
paroxysmal kinesigenic dyskinesia (1 paper, 2022). "In this study, we uncover egress from the Golgi as an important step in the biology of IFITM3 by identifying the domain that regulates this process and that similarly controls the egress of the dispanins IFITM1 and PRRT2, protein linked to paroxysmal kinesigenic dyskinesia." (PMID 35396335, 2022).
periodontitis (1 paper, 2022). An acute or chronic inflammatory process that affects the tissues that surround and support the teeth. "The ROC curves showed that the area under the ROC curve (AUC) for CRIP1 and IFITM1 in the healthy and periodontitis groups was 0.94 and 0.66, respectively (both p-values < 0.001)." (PMID 36329504, 2022). "An ELISA was conducted on the plasma of the healthy and periodontitis groups to measure changes in CRIP1 and IFITM1 protein concentrations, and compared with those of the inflammatory markers TNF-α, CRP, and ESR." (PMID 36329504, 2022). "Although there was a similar concentration of the three inflammatory indicators between the healthy and periodontitis groups, we found a difference in CRIP1 and IFITM1 levels." (PMID 36329504, 2022).
pituitary tumor (1 paper, 2026). A benign or malignant neoplasm affecting the pituitary gland. "IFITM1, which is known to regulate cell proliferation and migration, exerts tumor-suppressive effects in pituitary tumors; overexpression of IFITM1 markedly inhibits the proliferation of pituitary tumor-derived folliculostellate cells and induces apoptosis." (PMID 41200062, 2026).
PN tumor (1 paper, 2024). "IFITM1 protein levels were significantly decreased in MPNST tissues (P5 and P6) compared to those in benign PN tumor tissues (P1 and P3)." (PMID 39273214, 2024).
prostate adenocarcinoma (1 paper, 2022). "However, IFITM1 was significantly downregulated in some malignancies, such as kidney chromophobe (KICH), kidney renal clear cell carcinoma (KIRP), liver hepatocellular carcinoma (LIHC), and prostate adenocarcinoma (PRAD)." (PMID 36591519, 2022).
rectal cancer (1 paper, 2025). A primary or metastatic malignant neoplasm that affects the rectum. "Given that multifractionated ionizing radiation induces the expression of immune response genes in vitro, we additionally explored whether the PARPs are co-expressed with selected OAS2, IFITM1, and IFIT1 genes in rectal cancer patients." (PMID 40646573, 2025).
reovirus infection (1 paper, 2015). "Further, reovirus infection up-regulated the transcription of ISGs, namely IFITM1, ISG15 and Viperin, and blockage of the PI3K/Akt pathway in reovirus infection inhibited the expression of IFITM1, ISG15 and Viperin." (PMID 26388843, 2015).
sarcoidosis (1 paper, 2022). Sarcoidosis is a multisystemic disorder of unknown cause characterized by the formation of immune granulomas in involved organs. "Top up-regulated genes in sarcoidosis include interferon signature genes such as GBP5 and IFITM1, indicating active regulation of the interferon signaling." (PMID 36203777, 2022).
smooth muscle tumor (1 paper, 2025). A benign or malignant myomatous neoplasm arising from smooth muscle. "IFITM1 seems to outperform CD10 in distinguishing LG-ESS from smooth muscle tumors; however, larger studies are still needed to confirm its utility." (PMID 39836188, 2025). "Two studies report IFITM1 expression in 83% (10/12) and 100% (16/16) of LG-ESS cases, compared with 30% (6/20) and 40% (12/30) of smooth muscle tumors." (PMID 39836188, 2025). "The staining’s extent and intensity are also essential; tumors with diffuse, strong expression of multiple smooth muscle markers should be, in a proper morphological context, classified as smooth muscle tumors, even if there is a focal expression of CD10 or IFITM1." (PMID 39836188, 2025). "IFITM1 expression, while not entirely restricted to LG-ESS, tends to be weak and focal in smooth muscle tumors." (PMID 39836188, 2025).
Splenomegaly (1 paper, 2015). Abnormal increased size of the spleen. "We observed a dramatic increase in the expression of several proinflammatory markers such as Il17a, Ifnγ, Tnfα, IL-1β and Ifitm1, and chemokines such as Ccl1, Cxcl10, Ccl22 and Xcl1, in ATMINΔLNBS1ΔL mice displaying splenomegaly, compared to the other genotypes." (PMID 26544571, 2015).
stomach adenocarcinoma (1 paper, 2022). "For example, IFITM1 is a prognostic marker in resected esophageal and gastric adenocarcinoma." (PMID 36591519, 2022).
thyroid cancer (1 paper, 2019). "Some genes that we found to be epigenetically upregulated in OSCC-GB patients, such as PIK3CD and IFITM1, were earlier reported to be upregulated in thyroid cancer and HNSCC." (PMID 31796082, 2019).
tuberculosis (1 paper, 2020). A chronic, recurrent infection caused by the bacterium Mycobacterium tuberculosis. "In the current study, six genes (IFITM1, IRF9, MX1, OAS1, STAT1, and STAT2) of the “host response signature network” are significantly overlapping with the “human immune response to tuberculosis” pathway with p-value 1.57e-8." (PMID 33362771, 2020).
uveitis (1 paper, 2025). An inflammatory process affecting a part of or the entire uvea. "Several metaDEGs from the uveitis only group, including IFIT3, IFI44, IFITM1, MX1, TLR7 and DHRS9, and gene hubs from the modular co-expression analyses of the systemic disease-associated uveitis group are critical players in interferon-induced immune responses." (PMID 40270958, 2025).
vitiligo (1 paper, 2022). Generalized well circumscribed patches of leukoderma that are generally distributed over symmetric body locations and is due to autoimmune destruction of melanocytes. "Inflammatory and immune response–related genes such as CD74, IFI27, IFI6, and IFITM1 were also significantly increased, and this was further confirmed by the hallmark pathway enrichment analysis of the genes highly expressed in vitiligo lesional skin using the Molecular Signatures Database (MSigDB)." (PMID 35653192, 2022).